METTL3 (methyltransferase 3, N6-adenosine-methyltransferase complex catalytic subunit)
Diseases named in the same sentence as METTL3 in open-access papers (continued):
Sharing a sentence is not in itself a finding about the gene and the disease.
breast cancer (continued). "In breast cancer cells, METTL3 overexpression up-regulated the m6A methylation of PD-L1 mRNA and inhibited T-cell infiltration." (PMID 37907575, 2023). "METTL14, required for the catalytic activity of METTL3, was also upregulated in the breast cancer cell lines." (PMID 36725888, 2023). "To gain further insight into the molecular mechanism by which METTL3 promotes cell growth in breast cancer, we next performed RNA-seq upon silencing of METTL3 in MCF10-A, MCF7 and MDA-MB-231 cells." (PMID 36725888, 2023). "A recent study demonstrated that acetylation plays a role in regulating METTL3 localization and tumorigenic progression in breast cancer." (PMID 37391814, 2023). "In the spontaneously immortalized breast cancer cells (MCF10A), lowering m6A by knocking down Mettl3 caused the cells to become significantly more proliferative." (PMID 38023205, 2023). "Recent studies have shown that METTL3 is highly expressed in breast cancer and can be regulated by multiple noncoding RNAs such as miR-483-3p, let-7 g and pri-miR-221-3p." (PMID 36609396, 2023). "In breast cancer, metformin (a traditional diabetes drug) induced miR‐483‐3p expression and miR‐483‐3p was validated to target METTL3." (PMID 36162823, 2023). "This suggests the m6A via Mettl3 plays a significant role in mRNA regulation of EMT messages in breast cancer at all stages." (PMID 38023205, 2023). "To understand the mechanism by which METTL3 promotes glycolysis in breast cancer, we evaluated the effect of METTL3 on glycolysis in MCF-7 and T47D cells." (PMID 36609396, 2023). "BCL-2 was also the target of METTL3, which regulated breast cancer’s proliferation and apoptosis in a m6A modification pathway." (PMID 36970605, 2023). "The early-stage breast cancer line showed a more proliferative phenotype with the knockdown of Mettl3 while the transformed breast cancer line showed a more migratory phenotype." (PMID 38023205, 2023). "In breast cancer, METTL3, a host gene for circMETTL3, regulates circMETTL3 expression in an m6A-dependent manner." (PMID 37996892, 2023). "METTL3 promotes breast cancer lung metastasis by enhancing the stability of a keratin 7 (KRT7)-AS/KRT7 mRNA duplex and translation of KRT7." (PMID 39872957, 2023). "Nevertheless, our findings highlight that many biological processes occurring in breast cancer cells are regulated only by METTL3-induced AS, expanding the repertoire of functions of METTL3 in tumorigenesis." (PMID 36725888, 2023). "For instance, METTL3 posttranscriptionally upregulates PD-L1 expression in an m6A-IGF2BP3–mediated manner for enhancing stabilization of PD-L1 mRNA in breast carcinoma." (PMID 37063837, 2023). "METTL3 targeted MALAT1/miR-26b/HMGA2 axis and caused EMT and promotion of migration and invasion in breast cancer." (PMID 36212476, 2022). "We identify an IL-6-dependent positive feedback axis to facilitate nuclear METTL3 functions, eliciting breast cancer metastasis." (PMID 36289222, 2022). "All above results indicate that YHTDF1 is a reader protein of ARHGAP5 m6A in breast cancer cell lines and that METTL3/YTHDF1 controls ARHGAP5 protein levels with the translation modulation mechanism as the post-transcriptional axis." (PMID 36077054, 2022). "Studies showed that the increasing of METTL3 promoted proliferation and inhibited apoptosis in breast cancer by targeting Bcl-2." (PMID 35721510, 2022). "Upregulation of METTL3 is observed in breast cancer tissues and cells and its elevated expression is correlated with worse patient survival." (PMID 36008936, 2022). "Herein, we show that ADAR1, an A-to-I RNA-editing enzyme, interacts with METTL3 and increases its protein level to promote the proliferation, migration and invasion of breast cancer cells through a mechanism connecting ADAR1, METTL3 and YTHDF1." (PMID 36077054, 2022).
breast cancer (continued). "Our study laid a strong case for a novel mechanism of METTL3 function as an immunomodulator in the tumor microenvironment of breast cancer, in addition to regulating tumor progression." (PMID 35197058, 2022). "The positive feedback loop of HBXIP/let-7g/METTL3/HBXIP promotes the proliferation of breast cancer cells." (PMID 36008936, 2022). "We further confirmed that ARHGAP5 is a target of METTL3 in breast cancer and promotes the proliferation, invasion and migration of breast cancer cells." (PMID 36077054, 2022). "We performed a RIP experiment by using ADAR1 antibody to detect the interaction between ADAR1 and METTL3 mRNA in breast cancer cell lines." (PMID 36077054, 2022). "Together, these results indicate that m6A methylation of HOTAIR, particularly at A783, occur in breast cancer cells and is dependent on the METTL3/14 complex." (PMID 36441764, 2022). "METTL3 is an important methylase for m6A modification, and it shows important performance in lung cancer, breast cancer, ovarian cancer, gastrointestinal cancer, and leukemia by regulating downstream targets BCL-2, MEC6, and PTEN to inhibit apoptosis." (PMID 35141221, 2022). "Several studies have revealed that METTL3 regulated the expression of PD-L1 in bladder cancer and breast cancer." (PMID 36003776, 2022). "We found that both ADAR1 and METTL3 protein expression levels were increased in breast cancer tissues compared to normal adjacent tissues and in breast cancer cell lines compared to human breast epithelial cell MCF-10A." (PMID 36077054, 2022). "In Breast Cancer (BC), METTL3 overexpression enhanced the PDK4 protein expression in breast cancer cells." (PMID 35186927, 2022). "The finding that IL-6 mRNA underwent m6A modification prompted us to examine if IL-6 production positively correlated with nuclear METTL3 abundance in a panel of human breast cancer cell lines." (PMID 36289222, 2022). "To explore the clinical implications of METTL3 expression in breast cancer, particularly if its expression levels can distinguish breast cancer subtypes and histological grades, we assessed METTL3 expression in a cohort of 291 breast cancer patients." (PMID 36289222, 2022). "To date, METTL3, ALKBH5, FTO, and YTHDF2 have been implicated in promoting breast cancer tumorigenesis by affecting cancer cell survival/proliferation and cancer stem cell pluripotency 23-26." (PMID 35966596, 2022). "Metformin was found to inhibit the proliferation of breast cancer cells through upregulation of P21 in an m6A-dependent manner via METTL3." (PMID 35721510, 2022). "In MCF-7 breast cancer xenograft model, METTL3 contributes to the adriamycin resistance by promoting the maturity of pri-microRNA-221-3p in an m6A-dependent manner." (PMID 35804965, 2022). "METTL3 promotes m6A levels and docetaxel resistance in breast cancer by regulating the expression of LINC00662 and miR-186-5p; more experiments are needed to clarify the role of m6A regulation in drug resistance." (PMID 36202872, 2022). "METTL3 predicts shorter overall survival in glioblastoma, longer survival in breast cancer, and is also highly expressed in OV and promotes cell proliferation, lesion formation, movement, invasion, and tumor formation, and indicates poor prognosis." (PMID 35303965, 2022). "We identified that PD-L1 was a downstream target of METTL3-mediated m6A modification in breast cancer cells." (PMID 35197058, 2022). "METTL3 has been found to play an oncogene role in liver cancer and leukemia, while it exerts tumor inhibitive effect on cervical cancer and breast cancer." (PMID 36536402, 2022). "METTL14 stabilizes METTL3 and recognizes target RNA, which is found to be an oncogene or a tumor suppressor gene in breast cancer." (PMID 35721510, 2022). "METTL3 was demonstrated to upregulate PD-L1 expression via IGF2BP3 by m6A-dependent manner to modulate immune surveillance in breast cancer." (PMID 35721510, 2022).
breast cancer (continued). "For instance, expression levels of METTL3 in breast cancer are negatively correlated with CD8+ T cells, helper T cells and activated NK cells and positively correlated with TAMs." (PMID 35794625, 2022). "LINC00675 m6A methylation was increased by METTL3, which resulted in the interaction with miR-513b-5p and inhibition of cancerous properties of breast cancer." (PMID 35721510, 2022). "Another group identified that METTL3 can upregulate the expression of PD-L1 mRNA in breast cancer cells." (PMID 36212476, 2022). "Further, we found that ADAR1 expression was positively correlated with METTL3 expression in breast cancer samples in three different datasets." (PMID 36077054, 2022). "Screening and Identification of EGF as the targets of Methyltransferase-like 3 (METTL3) in breast cancer (BC)." (PMID 35502895, 2022). "METTL3 accelerates the maturation of pri-microRNA221-3p in a m6A-dependent manner, leading to adriamycin resistance in breast cancer cells." (PMID 35945641, 2022). "In this study, we found that ADAR1, an A-to-I RNA-editing enzyme, interacts with METTL3 mRNA and increases its protein level to promote the proliferation, migration and invasion of breast cancer cells through a mechanism connecting ADAR1, METTL3 and YTHDF1." (PMID 36077054, 2022). "Taken together, these results indicate that ADAR1 promotes the progression of breast cancer through METTL3." (PMID 36077054, 2022). "It is well-known that METTL3 plays an important role in promoting cancer proliferation in several human cancers, such as breast cancer, colorectal carcinoma, lung cancer, ovarian carcinoma, bladder cancer, and so on." (PMID 36058919, 2022). "Since breast cancer is a heterogenous disease divided into various molecular subtypes, METTL3 expression is found to be higher in normal-like and Luminal A/B subtypes compared to triple negative and HER2 positive subtypes." (PMID 36008936, 2022). "Public datasets were used to determine the prognostic potentials of ADAR1 and METTL3 in breast cancer." (PMID 36077054, 2022). "Meanwhile, we examined METTL3 localization in paired primary breast cancers and its metastatic lesions." (PMID 36289222, 2022). "In the current study, we identified PD-L1 as a downstream target of METTL3-mediated m6A modification in breast cancer cells." (PMID 35197058, 2022). "Together, these data suggest that ADAR1 promotes breast cancer tumor progression, likely by eliminating the inhibitory effect of miR-532-5p on METTL3 mRNA." (PMID 36077054, 2022). "In breast cancer, eight genes (METTL3, KIAA1429, ZC3H13, FTO, YTHDF1, YTHDF2, IGF2BP2, and IGF2BP3) were significantly enriched in tumor cells compared to immune or stromal cells." (PMID 35794212, 2022). "First, using multidimensional sequencing technology, we identified PD-L1 as a potential direct downstream target of METTL3-mediated m6A alteration in breast cancer cells." (PMID 35197058, 2022). "To further validate the correlation between METTL3 acetylation and tumor metastasis, we assessed acetyl-METTL3 levels by immunoprecipitating METTL3 from protein lysates extracted from fresh breast carcinoma samples." (PMID 36289222, 2022). "METTL3 can promote tumorigenesis and malignant progression and is highly expressed in a variety of malignant tumors, such as bladder cancer, breast cancer, and lung cancer." (PMID 34432955, 2021). "We detected correlation between METTL3 and circMETTL3 expression in breast cancer tissues and found the expression of circMETTL3 and METTL3 is positively correlated." (PMID 33867838, 2021). "For example, the m6A demethylase FTO promoted breast cancer progression by inhibiting BNIP313, and the HBXIP-elevated methyltransferase METTL3 promoted breast cancer progression by inhibiting the tumor suppressor let-7 g." (PMID 34151731, 2021). "Among these four m6A-associated genes, METTL3 promotes the development and progression of HCC, whereas it exerts a tumor-suppressive function in breast cancer." (PMID 34248650, 2021).
breast cancer (continued). "A recent study of triple-negative breast cancer (TNBC) also found that METTL3 expression is lower in breast cancer cells." (PMID 34044876, 2021). "METTL3 mRNA expression in breast cancer tissues was significantly higher than that in adjacent normal tissues." (PMID 33431790, 2021). "Hepatitis B X-interacting protein (HBXIP) upregulates METTL3 expression and then accelerates the proliferation of breast cancer cells by inhibiting the tumour suppressor let-7 g." (PMID 34044876, 2021). "For instance, HBXIP upregulates METTL3 expression in breast cancer cells by inhibiting miRNA-let-7g, which downregulates METTL3 expression by targeting its 3’-UTR." (PMID 34136491, 2021). "Knockdown of METTL3 inhibited the proliferation of breast cancer cells, whereas overexpression of METTL3 promoted the proliferation of these cells." (PMID 33431790, 2021). "IHC analysis showed that the expression of METTL3 in breast cancer tissues was positively related to tumor size and TNM grade." (PMID 33431790, 2021). "Xiaoping Pan at the Southern Medical University in Guangzhou, China, and co-workers examined the role of METTL3 in conferring resistance to the drug adriamycin in breast cancer cells." (PMID 33420414, 2021). "METTL3 can promote breast cancer cell proliferation by regulating p21 expression in an m6A-dependent manner." (PMID 34315512, 2021). "As a well-known candidate for drug repurposing in breast cancer, metformin exhibited antiproliferation activity in breast cancer via the miR-483-3p/METTL3/m6A/p21 pathway." (PMID 33431790, 2021). "Two independent previous studies showed that METTL3 had an oncogenic role in breast cancer through the diverse downstream targets such as tumor suppressor let-7g13 and bcl-235." (PMID 33431790, 2021). "Previous studies reported that METTL3 was able to promote breast cancer cell proliferation by regulating the expression of BCL-2, hepatitis B X-interacting protein (HBXIP) and p21 through m6A." (PMID 33879256, 2021). "We synthesized a distinct small interfering RNA (siRNA) targeting p21 (siP21) in METTL3 stable knockdown breast cancer cells to silence p21 in SUM-1315 and MCF-7." (PMID 33431790, 2021). "A recent study showed that METTL3 promotes adriamycin resistance of MCF-7 breast cancer cells by accelerating pri-microRNA-221-3p maturation." (PMID 34315512, 2021). "In breast cancer, the expression of METTL3 is decreased, which is closely related to short-term metastasis free survival." (PMID 34489709, 2021). "For example, METTL3 has been reported as an important oncogene in many tumor types, such as liver cancer, breast cancer and CRC." (PMID 34809621, 2021). "In breast cancer, METTL3 recognizes pri-miRNAs via the microprocessor protein DGCR8, increases mature miRNA levels, and decreases untreated pri-miRNA levels." (PMID 34136491, 2021). "Another study showed that METTL3 is highly expressed in clinical breast cancer samples and engages in a positive feedback loop, cooperated with HBXIP and let-7g miRNA (HBXIP/let-7g/METTL3/HBXIP), to accelerate proliferation in breast cancer." (PMID 34272618, 2021). "Previous studies showed these proteins played important roles in breast cancer developments 18-22, especially METTL3, which is the key component in methyltransferase enzymes 20, 23-25." (PMID 33867838, 2021). "In the present study, we found that METTL3 was significantly upregulated in breast cancer cell lines and tissues." (PMID 33431790, 2021). "Taken together, the differential functions of METTL3 were assessed in breast cancer, and various functions of METTL3 warrant further verification." (PMID 33879256, 2021). "In breast cancer, METTL3 is upregulated by HBXIP and promotes the cancer progression by suppressing let-7g." (PMID 34568001, 2021).
breast cancer (continued). "METTL3 negatively regulated the expression of p21 by influencing the mRNA stability of p21 and the antiproliferation activity induced by knockdown of METTL3 was rescued by silencing p21, which suggested that p21 was the main target of METTL3 in breast cancer." (PMID 33431790, 2021). "In summary, we provided compelling evidences showing that METTL3 markedly promoted breast cancer cell proliferation and high expression of METTL3 tended to be associated with poor clinical outcome in human breast patients." (PMID 33431790, 2021). "METTL3 is known to be able to promote breast cancer cell proliferation by regulating the p21 expression by an m6A-dependent manner." (PMID 33431790, 2021). "METTL3 promote tumor growth in breast cancer, lung cancer and liver cancer but as suppressor genes in Glioblastoma." (PMID 34521394, 2021). "MDA-MB-231 cells expressed a very low amount of METTL3 and cell growth inhibition by metformin was weaker than other breast cancer cell lines, further confirming the specificity of miR-483-3p/METTL3 axis as a target for metformin in breast cancer." (PMID 33431790, 2021). "They found that one microRNA, miR-221-3p, was overexpressed in chemoresistant breast cancer cells, via a signaling pathway involving METTL3." (PMID 33420414, 2021). "Taken together, we found that METTL3 promoted breast cancer cell proliferation by mediating p21 expression." (PMID 33431790, 2021). "To verify p21 as a downstream target of METTL3, we tested the mRNA and protein expression level of p21 in breast cancer cells." (PMID 33431790, 2021). "METTL3 was suggested to act as an oncogene in bladder cancer, breast cancer, ovarian carcinoma, and pancreatic cancer." (PMID 34234878, 2021). "It participates in the feedback loops of the HBXIP/METTL3 axis by N6-methyladenosine modification and regulates glucose metabolism in breast cancer." (PMID 35008539, 2021). "Other researchers have discovered that increased global m6A levels were present in breast cancer patients and that METTL3 knockdown enhances apoptosis by hindering m6A modification of the oncogene Bcl-2 and its translation." (PMID 34895230, 2021). "The METTL3 can inhibit the metastasis of breast cancer cells by increasing the methylation level of m6A and down-regulating the expression of COL3A1." (PMID 34489709, 2021). "Our study is one of the first studies to report that metformin showed antiproliferation effect on breast cancer as a novel METTL3 inhibitor." (PMID 33431790, 2021). "Transfection of breast cancer cells with miR-483-3p mimics led to a significant reduction of the METTL3 expression both at the mRNA and protein levels." (PMID 33431790, 2021). "In breast cancer, overexpressed METTL3 has been shown to increase HBXIP mRNA methylation, thereby promoting breast cancer cell proliferation." (PMID 34063990, 2021). "We can conclude that the m6A methyltransferase METTL3 controls epithelial-mesenchymal transition of breast cancer through the MALAT1/miR-26b/HMGA2 axis." (PMID 34419065, 2021). "In breast cancer, METTL3-induced LINC00958 upregulation affects tumorigenesis via the miR-378a-3p/YY1 axis." (PMID 34044876, 2021). "This study exhibited the pathway of miR-483-3p/METTL3/m6A/p21 involved in the anti-breast cancer activity of metformin." (PMID 33431790, 2021). "Metformin, a well-known drug repurposing candidate for breast cancer, exhibits antiproliferative activity in breast cancer cells through the miR-483-3p/METTL3/m6A/p21 pathway." (PMID 34858499, 2021). "MDA-MB-231 cells expressed a very low amount of METTL3 and the cell growth inhibition was weaker than other breast cancer cell lines significantly." (PMID 33431790, 2021). "The mRNA and protein levels of METTL3 were dramatically decreased in the breast cancer cell lines, especially in the TNBC cell lines." (PMID 35004298, 2021).